ZNF876P (zinc finger protein 876, pseudogene)
Description:
May be involved in transcriptional regulation.
Gene: Transcribed unprocessed pseudogene on chromosome 4 (218,650 to 254,841, forward strand). Ensembl gene ENSG00000198155.
Subcellular location: Nucleus
Diseases named in the same sentence as ZNF876P in open-access papers:
ZNF876P is named in the same sentence as 2 diseases in open-access papers, as found by Europe PMC text mining. Sharing a sentence is not in itself a finding about the gene and the disease. The quoted sentences say what the papers report.
meningioma (1 paper, 2020). A generally slow growing tumor attached to the dura mater. "Besides, potential roles of ABCA11P, ZNF732, and ZNF876P are novel in meningioma recurrence." (PMID 32923390, 2020).
ZNF876P also shares sentences with these, for which no sentence is quoted: cancer (1 paper).